ETFB (electron transfer flavoprotein subunit beta)
Description:
Heterodimeric electron transfer flavoprotein that accepts electrons from several mitochondrial dehydrogenases, including acyl-CoA dehydrogenases, glutaryl-CoA and sarcosine dehydrogenase. It transfers the electrons to the main mitochondrial respiratory chain via ETF-ubiquinone oxidoreductase (Probable). Required for normal mitochondrial fatty acid oxidation and normal amino acid metabolism. ETFB binds an AMP molecule that probably has a purely structural role.
Synonyms: FP585; MADD
Tractability: Small molecule: a structure with a bound ligand is known; it has a high-quality binding pocket. PROTAC: ubiquitination databases record sites on it; its protein half-life has been measured; a small molecule that binds it is known.
Gene: Protein-coding gene on chromosome 19 (51,345,161 to 51,366,449, reverse strand). Ensembl gene ENSG00000105379.
Subcellular location: Mitochondrion matrix
Subcellular location (Human Protein Atlas): Mitochondria
Pathways (Reactome):
Metabolism: Respiratory electron transport
Metabolism of proteins: Protein methylation
Gene Ontology:
Molecular function: electron transfer activity; protein binding
Biological process: amino acid catabolic process; fatty acid beta-oxidation using acyl-CoA dehydrogenase; respiratory electron transport chain
Cellular component: electron transfer flavoprotein complex; mitochondrial matrix; mitochondrion
Genetic constraint (gnomAD): Loss-of-function variants: 18 observed, 24.26 expected, observed/expected ratio (o/e) 0.74, 90% interval 0.51 to 1.1. The upper end of that interval is the gene's LOEUF score, 1.1, which puts it in group 4 of 6, group 1 being the genes least tolerant of losing a copy. Missense variants: 275 observed, 339.54 expected, observed/expected ratio (o/e) 0.81, 90% interval 0.73 to 0.89. Synonymous variants: 137 observed, 145.76 expected, observed/expected ratio (o/e) 0.94, 90% interval 0.82 to 1.08.
Gene-disease validity (ClinGen):
ClinGen rates the evidence that ETFB causes each of these diseases.
multiple acyl-CoA dehydrogenase deficiency (autosomal recessive): Definitive.
Homologues: Orthologues: chimpanzee ETFB (95% identical), pig ETFB (95% identical), dog ETFB (95% identical), macaque ETFB (94% identical), guinea pig ETFB (93% identical), rat Etfb (93% identical), mouse Etfb (92% identical), rabbit ETFB (86% identical), tropical clawed frog etfb (80% identical), zebrafish etfb (77% identical), Drosophila melanogaster Etfb (69% identical), Caenorhabditis elegans F23C8.5 (59% identical).
Diseases named in the same sentence as ETFB in open-access papers:
ETFB is named in the same sentence as 37 diseases in open-access papers, as found by Europe PMC text mining. Sharing a sentence is not in itself a finding about the gene and the disease. The quoted sentences say what the papers report.
multiple acyl-CoA dehydrogenase deficiency (22 papers, 2015 to 2026). "There is also a reported ClinVar missense variant for ETFB at K200 (p.Lys200Glu) of uncertain significance for Multiple acyl-CoA dehydrogenase deficiency (ClinVar Accession: VCV000459960.8)." (PMID 41509464, 2026). "There are several reported ClinVar variants for ETFB at K200, the residue tri-methylated in our study, associated with Multiple acyl-CoA dehydrogenase deficiency." (PMID 41509464, 2026). "The variants of electron transfer flavoprotein (ETFA, ETFB) and ETF dehydrogenase (ETFDH) are the leading cause of glutaric aciduria type II (GA-II)." (PMID 34573316, 2021). "In multiple acyl-CoA dehydrogenase deficiency (MADD), mutations in ETFa, ETFb, or ETFDH, lead to decreased ATP production with an accumulation of organic acids, including glutaric acid as well as acyl-carnitines." (PMID 32038305, 2019). "Glutaric acidemia type-II, caused by mutations of either ETFA, ETFB or ETFDH that collectively encode the OXPHOS enzyme electron transfer flavoprotein, is also characterized by PKD." (PMID 28205547, 2017). "Multiple acyl-CoA dehydrogenase deficiency (MADD) also known as glutaric academia type II or lipid-storage myopathy—is caused by loss-of-function variants in ETFDH, ETFA, ETFB or, more rarely, FLAD1." (PMID 40963932, 2025). "A prime example is multiple acyl-CoA dehydrogenase deficiency (MADD), caused by mutations in ETFDH, ETFA, or ETFB genes encoding electron transfer flavoprotein or its dehydrogenase." (PMID 40963932, 2025). "The multiple acyl-CoA dehydrogenase deficiency (MADD), also called GAII, is caused by genetic defects in the electron transfer flavoprotein ETF and its dehydrogenase ETFDH, which are encoded by ETFA, ETFB, and ETFDH, respectively." (PMID 40225143, 2023).
breast carcinoma (2 papers, 2019 to 2022). "However, recent studies have reported ETFB as a novel prognostic biomarker of many cancers, such as follicular carcinoma and breast cancer." (PMID 35359394, 2022).
acute myeloid leukemia (1 paper, 2024). Acute myeloid leukemia (AML) is a group of neoplasms arising from precursor cells committed to the myeloid cell-line differentiation. "In BC, the ETFB variants, related to the normal functioning of OXPHOS, have already been associated with a cardiotoxic effect, and their disfunction was related to lung cancer and acute myeloid leukemia." (PMID 39684297, 2024).
amyloidosis (1 paper, 2020). A disorder characterized by the localized or diffuse accumulation of amyloid protein in various anatomic sites. "We also profiled CSF in the 5xFAD mouse model to validate amyloidosis-induced changes, and found consistent mitochondrial decreases (SOD2, PRDX3, ALDH6A1, ETFB, HADHA, and CYB5R3) in both human and mouse samples." (PMID 32711556, 2020).
Encephalopathy (1 paper, 2023). Encephalopathy is a term that means brain disease, damage, or malfunction. "The metabolic decompensation may be life-threatening with encephalopathy and hyperammonemia, and neither clinical symptoms nor biochemical findings allow distinguishing RFVT1 deficiency from MADD deficiency (caused by biallelic ETFA, ETFB and ETFDH variants)." (PMID 37510312, 2023).
Familial adenomatous polyposis (1 paper, 2024). Familial adenomatous polyposis (FAP) is characterized by the development of hundreds to thousands of adenomas in the rectum and colon during the second decade of life. "The levels of both ETFB and pks+ Escherichia coli have been reported to be significantly increased in the intestinal mucosa of patients suffering from familial adenomatous polyposis (FAP)." (PMID 38792785, 2024).
heart failure (1 paper, 2021). Inability of the heart to pump blood at an adequate rate to meet tissue metabolic requirements. "Although the role of ETFB in the late stages of heart failure is not clear yet, a cohort study showed that ETFB is strongly associated with chronic ANT-induced cardiotoxicity." (PMID 34211507, 2021).
Hypoglycemia (1 paper, 2021). A decreased concentration of glucose in the blood. "In this study, six variants were found in two genes (ETFDH and ETFB) associated with GA-II, recurrent vomiting, and hypoglycemia." (PMID 34573316, 2021). "In one patient with persistent metabolic acidosis, hypoglycemia, and a high anion gap, the ETFDH:p.Gly472Arg, and ETFB:p.Pro94Thrfs*8 variants were identified in a homozygous, and heterozygous state, respectively." (PMID 34573316, 2021).
ischemic cardiomyopathy (1 paper, 2021). Ischemic cardiomyopathy is a cardiomyopathy in which a weakness in the muscle of the heart due to inadequate oxygen delivery to the myocardium with coronary artery disease being the most common cause. "Transcriptional repression of ETFB in ischemic cardiomyopathy is described." (PMID 34033948, 2021).
leukemia (1 paper, 2022). A malignant (clonal) hematologic disorder, involving hematopoietic stem cells and characterized by the presence of primitive or atypical myeloid or lymphoid cells in the bone marrow and the blood. "As AML is the second most common childhood leukemia, we utilized the TARGET pediatric study to analyze ETFA and ETFB expression and again found down-regulation or no significant change of ETFA and ETFB in most subtypes of AML." (PMID 35177813, 2022).
lung adenocarcinoma (1 paper, 2024). A carcinoma that arises from the lung and is characterized by the presence of malignant glandular epithelial cells. "Univariate Cox regression analysis suggested that the high expression levels of up-regulated DEGs including APOL1, ETFB, KLK8, PPP1R3G, PRL, and SPTA1 were significantly correlated with poorer overall survival (OS) in lung adenocarcinoma." (PMID 38183079, 2024).
organic acidemias (1 paper, 2021). "With the suspicion of organic acidemias early in her life, the coding regions and splicing sites of GCDH, ETFA, ETFB, ETFDH, IVD were evaluated by PCR and sequencing and no pathogenic variant was identified." (PMID 35083005, 2021).
Sepsis (1 paper, 2025). Sepsis is defined as life-threatening organ dysfunction caused by a dysregulated host response to infection. "Our team found that the expression levels of ACADVL, AFG3L2, ETFB, PCCB, and PCK2 were significantly overexpressed in ARDS samples compared to sepsis samples (all P value < .05), which was consistent with the results of bioinformatics analysis." (PMID 40068062, 2025).
cancer (3 papers, 2020 to 2024). A tumor composed of atypical neoplastic, often pleomorphic cells that invade other tissues. "Exome array analysis identifies ETFB as a novel susceptibility gene for anthracycline-induced cardiotoxicity in cancer patients." (PMID 38322112, 2024). "The most important gene was electron transfer flavoprotein beta subunit (ETFB, rs79338777), which participated in mitochondrial b oxidation and adenosine triphosphate (ATP) production, and whose association was replicated in a group of independent cancer patients treated with anthracyclines." (PMID 33110473, 2020).
metabolic disorder (2 papers, 2018 to 2025). "No additional genetic variants associated with metabolic disorders that cause increased C8 levels, such as mutations in the ETFA, ETFB, and ETFDH genes, were identified through high-throughput sequencing, leading to a final diagnosis of MCADD." (PMID 41002789, 2025). "During subsequent follow-up, consistently elevated levels of C8 and C8/C10 were observed, and high-throughput sequencing did not reveal any additional genetic metabolic disorders associated with elevated C8 (including variations in the ETFA, ETFB, and ETFDH genes)." (PMID 41002789, 2025).
adenocarcinoma (1 paper, 2022). A common cancer characterized by the presence of malignant glandular cells. "The genes in selected metabolic pathways in adenocarcinoma cells potentially regulated by these ligands were predicted as follows: ETFB, HS6ST2, and NDST1." (PMID 35954218, 2022).
myopathy (1 paper, 2014). A disease of the muscle in which the muscle fibers do not function properly. "In patients with muscular symptoms and histologically proven lipid storage myopathy but unremarkable metabolite patterns molecular analysis (starting with the ETFDH gene, followed by sequencing of ETFA and ETFB) is advisable." (PMID 25200064, 2014).
ETFB also shares sentences with these, for which no sentence is quoted: genetic diseases (2 papers); tumor (2); autism (1); autosomal recessive disease (1); bacterial infections (1); Behcet disease (1); brain malformations (1); cardiomyopathy (1); follicular carcinoma (1); fumarase deficiency (1); glutaric acidemia IIB (1); hydronephrosis (1); Hyperammonemia (1); ischemia (1); lipid storage myopathy (1); lung carcinoma (1); neurodevelopmental disorder (1); Obesity (1); Salmonella Infections (1); trisomy 21 (1).